INS (insulin)
Diseases named in the same sentence as INS in open-access papers (continued):
Sharing a sentence is not in itself a finding about the gene and the disease.
Hypoglycemia (continued). "It is also noted that the required insulin dose can be higher than expected to reach glycemic control and may increase hypoglycemia risk." (PMID 35627517, 2022). "However, its concentration increases due to hypoglycemia caused, e.g., by the presence of an insulin-producing tumor or overdose of insulin secretagogues, which provide important clues about the origin of hypoglycemia." (PMID 35324747, 2022). "Third, considering OGTT may cause the post prandial hypoglycemia episodes as glucose strongly stimulates the release of insulin, it is possible that the incidence of hypoglycemia was overestimated especially at post surgery visits." (PMID 36407309, 2022). "Therefore, this methodology holds the potential to reduce insulin needs and consequentially diminish the risk of its unwanted side effects (e.g., life-threatening hypoglycemia) while improving metabolic control." (PMID 35840613, 2022). "Obesogenic intrauterine environment can also explain the risk of increased fetal insulin production that may increase the risk of neonatal hypoglycemia." (PMID 35692979, 2022). "Humalog and NovoLog insulin are high-risk medications that require both therapeutic monitoring to ensure optimal short- and long-term outcomes and sufficient counseling for the prevention of adverse events such as hypoglycemia." (PMID 35156937, 2022). "Also, the present study found that the presence of NAFLD was associated with increased risk of severe hypoglycemia by 1.3-fold, a relatively modest association compared with established risk factors such as insulin or sulfonylurea use and CKD." (PMID 35195697, 2022). "In addition, glycemic fluctuation and insulin-related hypoglycemia are risk factors for increased postoperative complications and mortality." (PMID 35237639, 2022). "Therefore, postpartum insulin dosage should be reduced substantially to avoid the risk of hypoglycemia." (PMID 36339424, 2022). "Also, preserved beta cell function is reported to be related to a decreased risk of hypoglycemia and decreased insulin requirement." (PMID 35518934, 2022). "HI causes severe hypoglycemia due to the overproduction of insulin." (PMID 35573986, 2022). "Considering certain active comparators with an increased risk of hypoglycemia, such as sulfonylureas and insulin, might lead to a biased hypoglycemia evaluation, we conducted a further sensitivity analysis with only placebo-controlled RCTs." (PMID 36483741, 2022). "Another potential benefit of 24-h gastric enteral feeding in patients at high risk of RS is that it could limit postprandial insulin peaks related to carbohydrate load and, subsequently, reduce the risk of post-prandial hypoglycemia." (PMID 35011105, 2022). "In addition to causing hypoglycaemia, excessive and dysregulated insulin secretion suppresses the production of ketones, which normally act as an important alternative fuel to preserve neuronal function when there is insufficient glucose." (PMID 35928891, 2022). "The associated rise in glucose and increased closed-loop driven insulin delivery may result in hypoglycemia during exercise." (PMID 32914648, 2022). "There was a small increase in risk of hypoglycemia with dapagliflozin 2.5 mg that could be related to the studies included, which randomized patients on high doses of insulin to SGLT2 inhibitors." (PMID 35263050, 2022). "In contrast, this insulin gradient was lost in rats following subcutaneous insulin administration, which exhibited higher insulin concentration in the peripheral circulation and might cause hypoglycemia events." (PMID 36333321, 2022). "Hypoglycemia was associated with the use of insulin and sulfonylureas." (PMID 35770091, 2022). "These irregular dietary rhythms may lead to abnormal autonomic function and insulin secretion associated with hypoglycemia occurring throughout the day." (PMID 36303193, 2022). "However, lower insulin doses were associated with reduced prevalence of severe hypoglycaemia [3.5% vs. 5.9%, P = 0.02]." (PMID 35552566, 2022).
Hypoglycemia (continued). "Thus, enhanced insulin sensitivity associated with an additional insulin bolus injection in the evening would increase the risk of hypoglycemia even further." (PMID 36237197, 2022). "At the same time it increases the risk of postprandial hypoglycemia using a standard insulin dose." (PMID 35429987, 2022). "Eventually, the incidence of hypoglycemia in the standard fixed dosing group of females compared to males was more than the incidence of hypoglycemia in the weight-based insulin dosing group of females compared to males and increased the risk of hypoglycemia in females, as they reported." (PMID 36371171, 2022). "Also, ISPAD recommended insulin pumps to improve glycemic controls, reduce the risk of chronic complications, and reduce episodes of hypoglycemia." (PMID 36422210, 2022). "Researches postulated that the fear of hypoglycemia after exercise may be a possible cause for the patients to reduce their insulin dose." (PMID 36221091, 2022). "Ultra-long-acting analogues MAY BE CONSIDERED for basal insulin therapy in people at increased risk for hypoglycemia, as they are associated with a lower incidence of hypoglycemia and greater flexibility." (PMID 36510287, 2022). "The increased frequency of DKA observed in this subpopulation can be explained by the renal and pancreatic effects of SGLT2-inhibitors that are emphasized in patients in therapy with insulin, since to minimize the risk of hypoglycaemia it is necessary to further decrease the insulin dose." (PMID 36211584, 2022). "Moreover, these nanosystems have the beneficial feature of normoglycemic state detection, which is related to decreased insulin release when glucose levels are at normal rates, thereby avoiding the risk of hypoglycemia." (PMID 35215689, 2022). "Abnormalities in insulin diffusion with the risk of hypoglycemia could theoretically be observed when Glargine or Degludec insulin is administered in lipoatrophic areas." (PMID 35440056, 2022). "The diagnosis of insulinoma is reached by proving symptomatic hypoglycemia, generally below 50 mg/dl, in association with inappropriately elevated serum insulin (higher than 4 mU/l) and C-peptide levels during fasting, but can be established only with the criteria of the prolonged fasting test." (PMID 35838801, 2022). "The use of basal and postprandial insulin may be effective in controlling blood glucose levels; however, it requires more daily injections and increases the cost of treatment, risk of hypoglycemia, and risk of error in usage by patients." (PMID 35784980, 2022). "Thus, increased insulin signaling reduces the production of long-chain acylcarnitines; therefore, allowing glucose uptake and metabolism and increasing the risk of hypoglycemia." (PMID 36676928, 2022). "Association of NPH and premixed insulin and other predicted variables with hypoglycemia." (PMID 36149907, 2022). "Insulin therapy is considered the safest and most effective antidiabetic management in patients with chronic liver disease, but it is associated with an increased risk of hypoglycemia." (PMID 35252271, 2022). "This might be related to the risk of hypoglycemia in insulin users, while this risk is very low in DDP-4 and metformin treatment." (PMID 35337110, 2022). "In turn, less frequent inclusion of insulin may translate into higher postprandial glucose concentrations in the third trimester of pregnancy in mothers, thus increasing the risk of hypoglycemia in the newborn immediately after delivery." (PMID 35334574, 2022). "PA may increase the risk of hypoglycaemia due to an increase in insulin-stimulated glucose uptake into the muscles and an aerobic exercise-induced reduction of the blood glucose." (PMID 34427840, 2022). "Indeed, it has been previously shown that overactivation of the PI3K activity by mutations in its regulatory subunit in vivo increased insulin sensitivity and induced hypoglycemia." (PMID 35282439, 2022).
Hypoglycemia (continued). "However, lower insulin doses were associated with a reduced prevalence of severe hypoglycaemia (3.5% vs. 5.9%, P = 0.02)." (PMID 35552566, 2022). "A major risk of insulin therapy is hypoglycemia which is a risk factor for neurological damage." (PMID 36542240, 2022). "In addition, long-acting analogues are associated with a lower frequency of hypoglycemia vs NPH insulin in PWT1D." (PMID 36510287, 2022). "Insulin and sulfonylureas have higher risk of causing hypoglycaemia." (PMID 35684097, 2022). "Because patients treated with MDI have to make their insulin dosing decisions without access to the amount and timing of previous insulin doses or residual active insulin, this can, on the other hand, cause overlapping of insulin boluses and put a patient at risk of hypoglycemia." (PMID 35355552, 2022). "This outcome could reduce the risk of developing hypoglycemia, a common reported adverse effect associated with the use of insulin and insulin secretagogues in DM treatment." (PMID 35057487, 2022). "A potential explanation may be a protective effect of glucagon against acute hypoglycemia to counterbalance a strong insulin response to the glucose load and genetic variants involved in ion-channels regulating glucagon secretion." (PMID 36686477, 2022). "To reduce the risk of hypoglycemia in older patients, we can do as follows: 1) Before starting insulin, the benefit of insulin therapy and the risk of hypoglycemia in older diabetic patients should be fully considered, and individualized treatment regimen should be developed." (PMID 36249753, 2022). "Data from advanced hybrid closed loop (AHCL) systems clearly show that the timing of bolus remains critical to achieve optimal glycemic targets, and a delayed administration may cause automated over-delivery of insulin and subsequent hypoglycemia." (PMID 36556278, 2022). "In the hours following PA, insulin sensitivity is increased, and muscle and hepatic glycogen content need to be restored which results in glucose being diverted from the blood, increasing the risk of hypoglycemia." (PMID 36237197, 2022). "Since the patient had high titers of IAs as well as undetectable C-peptide and endogenous insulin, we speculated that the spontaneous hypoglycaemia in our patient was possibly caused by dysfunctions of injected insulin due to the presence of IAs." (PMID 36440205, 2022). "This study aimed to determine whether an MPC algorithm-based artificial pancreas system might be more effective than conventional insulin therapy in terms of hypoglycemia risk and maintaining glucose levels within the target range in outpatients with T1D." (PMID 36494830, 2022). "Excessive insulin doses, may cause hypoglycemia, that is, low blood glucose levels, which can lead to short-term complications, such as drowsiness, shakiness, confusion, loss of consciousness, seizure, or even coma or death." (PMID 36099285, 2022). "Finally, the iatrogenic causes of hypoglycaemia include the administration of drugs like insulin and sulfonylurea." (PMID 36288153, 2022). "Moreover, their intrinsic effects on insulin and glucagon are tailored in a glucose-dependent manner, thus posing a low risk of hypoglycemia and making them one of the most effective and safest options when a more intensive antidiabetic treatment is required." (PMID 35429298, 2022). "A more stable and precise administration of the intended insulin dose from the start of therapy may reduce the risk of hypoglycaemia." (PMID 36542240, 2022). "In the paper by Wang, G.., hysteresis in insulin action is hypothesized to cause postprandial hypoglycemia." (PMID 36148302, 2022). "Therefore, for Chinese T1DM patients, in order to assess the potential role of insulin pumps in reducing the risk of hypoglycemia, the insulin delivery and insulin regimen are equally important." (PMID 36091534, 2022).
Hypoglycemia (continued). "A previous report showed that insulin and blood glucose levels measured in hospitalized patients with BN decreased rapidly after vomiting the test meal and that hypoglycemia due to vomiting could be associated with binge eating and purging cycles." (PMID 36303193, 2022). "We undertook this study to specifically analyze the potential risk of overtreatment defined as an HbA1c < 7% or an HbA1c < 6.5% in patients aged 75 years or older treated with drugs associated with a higher risk of hypoglycemia (insulin, sulfonylureas, or glinides)." (PMID 36079064, 2022). "Insulin overdose is the most common risk factor for hypoglycemia." (PMID 35207323, 2022). "However, there is also the biggest risk of the usage of this device which is hypoglycemia due to an over delivery of insulin, excessive physical exercise, and consumption of alcohol." (PMID 36411933, 2022). "Therefore, when ARNI is used in combination with hypoglycemic drugs, we suggest closely monitoring blood glucose and appropriately reducing the dose of insulin secretagogue or insulin in patients with a high risk of hypoglycemia to reduce this risk." (PMID 35928297, 2022). "Furthermore, human native insulin contributes to the risk of hypoglycemia and poor pharmacokinetic profiles with unpredictable absorption rates and action." (PMID 35890301, 2022). "Insulinomas are insulin-producing tumors of pancreatic beta cells that cause hypoglycemia." (PMID 36290169, 2022). "When comparing basal-bolus insulin with premixed insulin, glucose variability was similar, but the premixed insulin group had an 8% higher percentage of glucose values in the target range, alongside a trend towards a lower risk of hypoglycemia (19.1% vs. 13.3%)." (PMID 34986826, 2022). "Sitagliptin induces glucose-dependent insulin release, so it rarely causes hypoglycaemia." (PMID 36355535, 2022). "However, there is still a need to identify other hormonal and physiological insulin/IGF-1 independent activators of Akt to avoid associated side effects such as hypoglycemia when used therapeutically." (PMID 36169399, 2022). "On the other hand, excess insulin administration may also cause hypoglycemia followed by coma and even the risk of death." (PMID 36405706, 2022). "Starting at a lower dose and gradually increasing, it reduces the risk of hypoglycaemia in the early period of therapy, provides time for incorporation of insulin therapy into daily routine, time to adjust concomitant treatments, and time for additional education." (PMID 33098260, 2021). "It has been suggested that high insulin doses, e.g. ≥ 1 U/kg/d., may be needed to normalize blood glucose, but this may be at the cost of a high risk of hypoglycemia." (PMID 35069449, 2021). "None of the FAHFAs we tested potentiated GSIS in the presence of a low glucose concentration (2.5 mM) in MIN6 cells, which is advantageous because augmentation of insulin secretion at a low glucose concentration could cause serious hypoglycemia." (PMID 34418413, 2021). "Continuous self-caring and hypoglycemia disruptions easily cause stigma, becoming bullying targets and conflict situations all practices associated to disease management (capillary blood glucose tests, insulin injections and dietary restrictions)." (PMID 33672506, 2021). "The most frequent triggering causes of hypoglycemia were carbohydrate deficit (including ‘missed or delayed meal’ and ‘meal inappropriately low in carbohydrates’) (54.0%), acute illness (40.2%) and related to insulin therapy (34.3%)." (PMID 33402217, 2021). "However, EIAS is caused by IAA against exogenous insulin, which can bind endogenous and exogenous insulin and cause poor glycemic control and hypoglycemia by a mechanism similar to IAS." (PMID 33827670, 2021). "Insulin used in the treatment of diabetes is among the common causes of hypoglycemia." (PMID 33564529, 2021).
Hypoglycemia (continued). "Despite this, there may be an increased risk of hypoglycemia when combining basal insulin with sulfonylurea; both agents are associated with hypoglycemic events, albeit that newer sulfonylureas (glipizide, glimepiride, and gliclazide) may carry a lower risk." (PMID 34165382, 2021). "This is a common problem and a major cause of insulin-induced hypoglycemia." (PMID 33556090, 2021). "Indeed, proinsulin-secreting neuroendocrine tumors causing hypoglycemia with insulin concentrations below diagnostic thresholds have been reported." (PMID 34051096, 2021). "We reasoned that the results of GTT obtained from sunitinib-treated rats might be associated with an enhanced glucose-induced insulin secretion and the impaired renal insulin clearance, which may lead to spontaneous hypoglycemia." (PMID 33841146, 2021). "Both groups had normal HbA1c glycosylation levels, and overweight was lower in patients taking insulin Detemir than in NPH patients, while hypoglycemia has been lower in patients treated by insulin Detemir; and the weight loss of the patients was attributed to insulin Detemir." (PMID 34904015, 2021). "Insulin quickly absorbed into the muscle layer may cause hypoglycemia, and rotational insulin injection is recommended to prevent lipohypertrophy." (PMID 36311443, 2021). "All this occurs independently of insulin secretion, so the risk of hypoglycemia is minimal." (PMID 34790827, 2021). "On the other hand, both sulfonylurea and systemic insulin treatment are associated with the risk of hypoglycemia, which may contribute to dementia incidence." (PMID 34857046, 2021). "On the other hand, intensive insulin treatment might increase risk of hypoglycemia, especially in T1DM patients who had poor islet function." (PMID 34819569, 2021). "Metformin reduced fasting serum insulin by 40 % hence the risk of hypoglycemia is minimal." (PMID 33588801, 2021). "Indeed, SIRT6-knockout micedisplay increased glycolytic pathway associated with high glucoseuptake, increased insulin signaling, and severe hypoglycemia as acompensatory response." (PMID 34213345, 2021). "N-3 PUFA increases endogenous insulin production, resulting in reduced daily insulin doses, better metabolic control, reduced risk of long-term diabetic complications, and adverse effects of intensified insulin therapy, primarily hypoglycemia." (PMID 34959363, 2021). "Insulin analogs with an extremely short or an extremely long duration of action are now in use, and in T2D older drugs such as sulfonylureas are less and less in use, due primarily to their significant risk of hypoglycemia." (PMID 34638984, 2021). "However, many patients with T1D are concerned about undertaking exercise because of the risk of developing hypoglycaemia and how to adjust their insulin or carbohydrate intake to prevent aberrations in their glycaemic control." (PMID 33914197, 2021). "As a group with prior risk of severe hypoglycemia, our study patients who received insulin analogues via administrative proceedings abided to the requirement of the dispensing protocol, in which the presence of at least two events of severe hypoglycemia within 6 months was one of the criteria." (PMID 33905628, 2021). "In insulin treated GDM patients, the increasing insulin resistance during pregnancy causes specific challenges for exercise prescription, as adjustments on insulin doses and carbohydrate intake are required to prevent hypoglycemia during and after training." (PMID 33870263, 2021). "However, antidiabetic agents, which increase insulin production and exogenous insulin levels, are the most common causes of hypoglycemia." (PMID 34342593, 2021). "Interestingly, in comparison with diabetic rats, insulin administration to induce recurrent episodes of hypoglycemia caused a significant recovery in body weight and a significant decrease in glycated hemoglobin values." (PMID 34948265, 2021).